SETD2 (SET domain containing 2, histone lysine methyltransferase)
Diseases named in the same sentence as SETD2 in open-access papers (continued):
Sharing a sentence is not in itself a finding about the gene and the disease.
tumor (continued). "To better understand the role of the SETD2 in tumor metabolism in RCC progression, we systematically investigated the function of SETD2 in PKD-ccRCC transition based on comprehensive analyses of transcriptomics, proteomics, lipidomics and metabolomics." (PMID 37989747, 2023). "A clonal nonsense driver mutation in SETD2 was lost at relapse, and several subclonal variants were observed in ALK and MYCN in <5% of the tumor cells, which is often observed in highly amplified oncogenes." (PMID 36867694, 2023). "A significant difference in CNV is also observed between SETD2 wt and SETD2 mt tumor regions (p = 1.4 × 10–9), with higher CNV in the former." (PMID 37120552, 2023). "SET domain–containing 2 (SETD2) has been identified as an important tumor suppressor and an immunosuppressor in ccRCC." (PMID 37989747, 2023). "SETD2-H3K36me3 is key component of common tumor suppressor mechanisms and an important target for cancer diagnosis and treatment." (PMID 37359376, 2023). "In a study performed by Yuan and others by assessing the tumor-suppressive function of SETD2 in PCa, it was clearly demonstrated that SETD2 monomethylates EZH2 at its 735 lysine residue, triggering a Smurf2 E3 ligase-dependent degradation." (PMID 37228649, 2023). "Other driving mutations, including SETD2, PBRM1 and BAP1, lead to genomic instability and promote tumor cell metastasis through the disorder of various metabolic and immune response pathways." (PMID 36966163, 2023). "SETD2 stabilization increases cell proliferation contrary to its canonical role as a tumor suppressor." (PMID 37025591, 2023). "We also overexpressed SETD2 in ACHN cell lines and found that overexpression of SETD2 decreased the sensitivity of tumor cells to erastin." (PMID 37604811, 2023). "SETD2 functions as a tumor suppressor in different stages of pancreatic carcinogenesis, and SETD2/H3K36me3 simultaneously inhibits acinar-ductal reprogramming and EMT." (PMID 37359376, 2023). "In the present study, we found that the epigenetic molecule, SETD2, increases the sensitivity of the ferroptosis inducer, erastin, further promoting ferroptosis in tumor cells." (PMID 37604811, 2023). "SETD2-H3K36me3 is a common oncogenic mechanism in tumors, and its regulatory mechanism is tumor tissue specific." (PMID 37359376, 2023). "Overall, SETD2 wt/H3K36me3-positive tumor regions showed more epigenetic and genetic level ITH, suggesting that SETD2 mutations drive an epigenetic landscape that promotes a distinct and more homogeneous epigenome associated with adverse outcomes." (PMID 37120552, 2023). "In our cohort, SETD2 alternated in all 6 tumor samples (2 primary tumors and 4 lymph node metastasis) of the Patient1, including 5 splice site mutations and 1 missense mutation." (PMID 36653483, 2023). "Above all, alternative approaches, including miRNA-based regulation, focus on restoring the expression of tumor-suppressive PKMTs, including SETD2, to counteract tumorigenesis." (PMID 38036730, 2023). "In our study, we analyzed the FoxP3 transcriptome across TCGA cancers, and we found that the FoxP3 was highly expressed in the tumor tissues of ccRCC patients with BAP1- or SETD2-mutant genotype." (PMID 37569676, 2023). "Mutational ITH was also observed among epigenetic regulators, including SETD2 and KDM5C, which sustained multiple unique and spatially distinct inactivating mutations within individual tumor regions." (PMID 37120552, 2023). "SETD2 is a histone H3K36 trimethyltransferase, and its mutation is widespread in diverse tumor types and accounts for 5% of all cancers in the TCGA cohort (521/10953)." (PMID 36453584, 2023).
tumor (continued). "Herein, we perform systematic multi-omics characterizations on PKD mice (driven by c-MYC) and ccRCC mice (driven by c-MYC and Setd2 knockout) to investigate SETD2 function in tumor metabolism during PDK-ccRCC transition." (PMID 37989747, 2023). "These biological functions of SETD2 in hematopoietic stem cells provide insight into the role of SETD2 as a tumor suppressor." (PMID 38036730, 2023). "In conclusion, the in-depth study of SETD2 during tumor formation and development is warranted for diagnosing, treating, and preventing tumors." (PMID 37025591, 2023). "We also confirm that SETD2 is a tumor suppressor in ccRCC, along with the decreased SETD2 protein level in advanced tumor stage, and knock-down of SETD2 leads to the promotion of cell proliferation, migration, and invasion." (PMID 38868222, 2023). "As a functional DDR is critical for maintaining genome integrity and preventing tumor development, SETD2 is considered as a putative tumor suppressor gene in cancers." (PMID 37759431, 2023). "Strikingly, homozygous deletion of Setd2 accelerated the initiation of KrasG12D lung tumors, increased tumor burden, and significantly reduced mouse survival." (PMID 36810256, 2023). "SETD2 is a known tumor suppressor and is involved in several molecular pathways that maintain genomic stability." (PMID 35581654, 2022). "A more fundamental insight in the role of SETD2 in transcriptional interference in mammalian cells would greatly contribute to understanding any potential role of this process in tumor progression." (PMID 35661267, 2022). "It is also suggested that BAP1, SETD2, and PBRM1 are prevalent co-drivers of tumor grade and invasion of ccRCC and associated with aggressive progression." (PMID 35979371, 2022). "In vitro experiments indicated that SETD2 knockdown upregulated tumor cell apoptosis, attenuated proliferation and migration of LUAD cells, and enhanced their radiosensitivity." (PMID 36035179, 2022). "cGAS-STING pathway, an important pathway regulating host innate immunity, has been successively validated in various tumor models where SETD2 is an important epigenetic regulator." (PMID 36713412, 2022). "We next investigated the effects of SETD2 on tumor malignant behaviors and radiosensitivity in vitro." (PMID 36035179, 2022). "Genes highly expressed in SETD2-positive tumor cells were enriched in DDR, RNA splicing, and histone modification signals." (PMID 36035179, 2022). "In immunohistochemistry of 5 LUAD and 3 normal lung tissues from the HPA database, we compared SETD2 staining scores of tumor and alveolar cells." (PMID 36035179, 2022). "That is, VHL mutation acts as an initiative event to induce tumor occurrence, while PBRM1, BAP1 and SETD2 cause DNA repair defect and cell overgrowth." (PMID 35918352, 2022). "So far, SETD2’s tumor-suppressor function has mostly been attributed to its chromatin-associated roles in transcription regulation, mRNA processing and maintaining genome stability." (PMID 35661267, 2022). "Fundamental insights into the functions of SETD2 are required to understand its tumor-suppressor function." (PMID 36052643, 2022). "Additional driver mutations (SETD2, PBRM1, BAP1, and others) promote genomic instability and tumor cell metastasis through the dysregulation of various metabolic and immune-response pathways." (PMID 36428521, 2022). "Decreased SETD2 expression predicted unfavorable prognosis (larger tumor size and advanced pT stage) in patients with ccRCC." (PMID 35055428, 2022). "As a tumour suppressor, SETD2 plays an important role in gene transcription regulation, DNA damage repair and alternative splicing." (PMID 33949020, 2021).
tumor (continued). "More precise clarifications of which kind of role does SETD2/H3K36me3 plays in sacral chordoma, a carcinomic factor or tumor suppressor, require further evidence." (PMID 34715919, 2021). "Of note, the variant frequencies in the clonal tumor population (ARID2, SETD2, and TERT promoter) and in the subclonal population (NF2) were validated by targeted NGS for this patient." (PMID 34261524, 2021). "The loss of 3p as the first event typically occurs 5–20 years before tumor diagnosis, and PBRM1, BAP1, and SETD2, which are commonly observed in other mutated genes in sporadic ccRCC, are coincidentally located on chromosome 3p." (PMID 34575959, 2021). "Consistent with previous reports, the classical driver mutations associated with ccRCC, including alterations in VHL, PBRM1, BAP1, and SETD2, were identified in tumor samples." (PMID 33806963, 2021). "In contrast, other driver mutations, such as MTOR, PTEN, SETD2, and KDM5C, exhibited intra-tumor heterogeneity." (PMID 34575959, 2021). "Further detection has shown that the expression of SETD2 is negatively correlated with tumor grade, stages and lymph node metastasis." (PMID 32231741, 2020). "In the present study, we showed that SETD2 functioned as a putative tumor suppressor in LUAD using human LUAD tissue specimens and cell lines in combination with gene expression profile obtained from The Cancer Genome Atlas (TCGA)." (PMID 33223508, 2020). "The tumor suppressor gene SETD2 is a histone methyltransferase that functions to trimethylated lysine 36 in histone H3." (PMID 32849799, 2020). "The results exhibited that circ_SETD2 overexpression repressed tumor growth (reduced tumor volume and weight) compared to the vector group." (PMID 33336052, 2020). "In pRCC2 tumors, we observed a SMARCB1 driver mutation in one pRCC2; TERT promoter in two pRCC2; SETD2, PBRM1 and NF2 in one pRCC2 tumor each." (PMID 32555180, 2020). "SETD2 is the only methyltransferase for H3K36me3, and our previous study has firstly demonstrated that it functioned as one tumor suppressor in hematopoiesis." (PMID 33292784, 2020). "The results have shown that the SETD2 expression at the mRNA and protein levels is remarkably lower in tumor tissue compared with adjacent normal tissue, and the SETD2 expression at the mRNA level is declined in nearly 80% tumor tissue samples." (PMID 32231741, 2020). "In the presence of chromosomal translocation, such as MLL-rearrangement, knockdown of SETD2 promotes initiation as well as progression of tumor by expediting the potential of self-renewal of leukemic stem cell." (PMID 30922329, 2019). "For SETD2 involving in tumor initiation, progression as well as chemosensitivity through different mechanism." (PMID 30922329, 2019). "Previously we have revealed that SPOP promotes the degradation of SETD2, an important tumor-suppressor in many cancers, through poly-ubiquitination." (PMID 30237511, 2019). "Such roles for Set2 in maintaining genome stability help explain the tumour suppressor function of the human orthologue, SETD2." (PMID 30674555, 2019). "SET domain containing 2 (SETD2), a histone methyltransferase that is specific for tri-methylation of Histone3 at lysine 36 (H3K36me3), has been shown to act as a tumor suppressor in human cancers." (PMID 31590683, 2019). "In a study of four patients, VHL mutation and 3p loss of heterozygosity were found in all regions of the tumor samples (trunk), while other common mutations recognized as driver mutations (SETD2, PBRM1, MTOR, SETD2, BAP1, KDM5C, TSC1)." (PMID 31207938, 2019).
tumor (continued). "Exceptions included events private to the primary tumor (SETD2 and ARID1A in LUAD6; NOTCH2 in SCLC1), or private to metastases (SMARCA4 in LUAD5; ARID1A in LUAD7)." (PMID 30348992, 2019). "It is noteworthy that a recent report by Dr. Sandeep S. Dave’s group identifies Setd2 as the most frequently mutated gene in enteropathy-associated T cell lymphoma (EATL), a neoplastic disease derived from γδ T cells." (PMID 31350389, 2019). "In many cases the protein expression levels of PBRM1, SETD2 or BAP1 correlated with that of STAT2 or IRF9 on the same tumor samples." (PMID 30355451, 2018). "Its inhibitory effect on tumor growth can be relieved by the loss of PBRM1, KDM5C, SETD2 or BAP1 to promote robust tumor growth." (PMID 30355451, 2018). "Physiologically, SETD2 plays an important role in tumor suppression, aging delay, and antiviral immunity." (PMID 30422989, 2018). "This is surprising, because SETD2 has been implied to have tumor suppressor activity in various malignancies, including leukemia." (PMID 29777171, 2018). "As with VHL, PBRM1 and SETD2, biallelic inactivation of BAP1 via mutation and loss of heterozygosity fit a two-hit tumor suppressor profile." (PMID 30355451, 2018). "Clear cell RCC (ccRCC) is the most common (∼80%) subtype and is characterized by bi-allelic loss of tumour suppressor genes on chromosome 3p, the most common of which are VHL, PBRM1, SETD2 and BAP1 (refs 15, 16)." (PMID 28489074, 2017). "We found limited genetic concordance between primary and secondary tumor sites with private mutations in FLT4, MTOR, ITGA5, SETD2, PBRM1, and BRCA1 on progression." (PMID 29088767, 2017). "SETD2 is the only known gene that can catalyze H3K36 trimethylation, and loss-of-function mutation of SETD2 eventually decreases H3K36 trimethylation and contributes to tumor development." (PMID 28852847, 2017). "In recent years, SETD2 has attracted a lot of interest as a gene whose inactivation is involved in tumor initiation and progression." (PMID 27191891, 2016). "Ectopic gains in H3K36me3, which occur less frequently than losses of H3K36me3, were also conserved, but excluded from the SETD2 WT tumor sample." (PMID 26646321, 2016). "In ccRCC, SETD2 is ranked in the top-5 most commonly mutated genes (COSMIC, rank 4), indicating its specific role in this tumor type." (PMID 27191891, 2016). "Additional proof for a tumor suppressor role of SETD2 came from Sleeping Beauty transposon experiments." (PMID 27191891, 2016). "PPP2R1A (E370X), SETD2 (I1608V), SMAD4 (G382T), and AR splicing site mutations were determined to be potential metastatic tumor-specific mutations." (PMID 27023146, 2016). "In combination with the presence of SETD2-inactivating mutations in a substantial proportion of ccRCC, this clearly demonstrates SETD2′s role as a suppressor of both tumor initiation and progression." (PMID 27191891, 2016). "In patient AML#2, we detected a frameshift insertion (c.6306_6307insCACC, p.P2102fs) of gene SETD2 in a considerable fraction of the tumor population both at diagnosis (MF 32.5%) and at relapse (MF 31.7%)." (PMID 27462774, 2016). "To better understand the effect of DNA hypermethylation resulting from SETD2 inactivation in primary tumors, we examined CpGs hypermethylated across all three tumor types (KIRC, KIRP, and LuCa) to determine if there was a common 5mC signature of SETD2 loss." (PMID 26646321, 2016). "HR repair and DNA MMR defects have been observed in SETD2-inactivated tumor cell lines, although the repair machineries themselves are not abolished in these cells." (PMID 27191891, 2016). "Recent comprehensive genomic analyses of ccRCC revealed in addition to VHL mutations, recurrent mutations in several other ccRCC tumor suppressor genes including PBRM1, SETD2, and BAP1." (PMID 25826081, 2015).
tumor (continued). "This was evidenced most strikingly in the parallel evolution of tumour RK36 that acquired three distinct, truncating SETD2 mutations associated with deletions of different 3p haplotypes in three regions out of nine tested." (PMID 25790038, 2015). "In the current study, we have used 2 major databases to identify a compound, TGX221 not previously studied in ccRCC that has strong selectivity for tumours having VHL, SETD2, PTEN and CDKN2A mutations." (PMID 25853938, 2015). "The histone methyltransferase gene SETD2/HYPB, located at 3p21.31, was identified as a novel tumor suppressor gene in RCC." (PMID 24959214, 2014). "Based on our cohort (n = 14), we estimate that among patients harboring a mutation in PBRM1, SETD2, BAP1, or KDM5C, the mutation would be present in 75%, 70%, 58%, and 55% of the tumor, respectively." (PMID 25124064, 2014). "In our cohort, we estimated that a minimum of three tumor regions must be sampled to detect mutations in PBRM1, SETD2, BAP1, and/or KDM5C with 90% certainty." (PMID 25124064, 2014). "For example, all the SETD2 and BAP1 somatic mutations and the majority of PBRM1 mutations were found in the branches of the tumor phylogenetic trees." (PMID 25159823, 2014). "Based on the mutations' prevalence we estimated that three different tumor regions should be sampled to detect mutations in PBRM1, SETD2, BAP1, and/or KDM5C with 90% certainty." (PMID 25124064, 2014). "The levels of SETD2 mRNA were significantly lower in malignant samples (p = 0.0345) and decreased with increasing tumour stage." (PMID 19698110, 2009). "Based on the biological function of these genes, SETD2 is the most likely gene to play a tumour suppressor role and explain our previous findings." (PMID 19698110, 2009). "Subsequently, a series of in vitro and in vivo experiments revealed that LEDGF binds H3R17me2a to regulate purine nucleotide metabolism in SETD2 mutant ccRCC cells, promoting tumor proliferation, and may be an effective therapeutic target." (PMID 40548925, 2025). "This suggests a destabilization of the integrity of the nuclear lamina and genome instability, which could enable SETD2 to play its role as a tumor suppressor by controlling the disassembly of the nuclear envelope during the cell cycle." (PMID 39591760, 2025). "In the genomic analysis of the primary tumor tissue of the TRACERx Renal study, the multi-region sequencing underscores intratumoral heterogeneity and validates clonal mutual exclusivity patterns associated with BAP1 and PBRM1/SETD2." (PMID 41440218, 2025). "SETD2 inactivation can affect tumor immune microenvironment to enhance neutrophil recruitment." (PMID 40959108, 2025). "Similar tumor-suppressive roles of SETD2 have also been reported in other cancer types." (PMID 41013841, 2025). "Collectively, LEDGF binds H3R17me2a to regulate purine nucleotide metabolism in SETD2 mutant ccRCC cells, promoting tumor proliferation, and may be an effective therapeutic target." (PMID 40548925, 2025). "Moreover, SETD2 depletion accelerated tumorigenesis as measured by a modest increase in tumor nodule numbers and a four-fold increase in tumor burden." (PMID 40462961, 2025). "While these studies demonstrate that CRISPR-mediated endogenous depletion of SETD2 or homozygous genetic deletion of SETD2 promote tumorigenesis, future work will help elucidate the specific contributions of H3K36me3 synthesis and other SETD2 functional domains in tumor suppression." (PMID 40462961, 2025). "Whether SETD2-mediated catalysis of H3K36me3 is tumor suppressive or oncogenic in a tumor context-dependent manner—and how this activity relates to SETD2’s other functions—are potentially important questions for future investigation." (PMID 40462961, 2025). "Notably, knockout of known tumor suppressors SetD2 and Smad4 maintained normal tumor growth, confirming the specificity of our approach." (PMID 41472851, 2025).